INS (insulin)
Diseases named in the same sentence as INS in open-access papers (continued):
Sharing a sentence is not in itself a finding about the gene and the disease.
Insulin resistance (continued). "In all groups, serum triglycerides, insulin levels, serum HDL and insulin resistance improved after the 6-month intervention." (PMID 22299005, 2011). "Present therapies to minify hyperglycaemia and insulin resistance mainly target ATP-sensitive K+ channels (KATP) of pancreatic cells and PPAR-γ to enhance the insulin secretion and potential for GLUT expression, respectively." (PMID 22028710, 2011). "HOMA-IR, which is calculated from fasting plasma glucose (FPG) and insulin (FIRI), is highly correlated with the Clamp-IR; therefore it is a useful surrogate index of insulin resistance in both healthy and diabetic subjects." (PMID 21831271, 2011). "In contrast, the long-term upregulation of catecholamines, often present in patients with heart failure, antagonizes the actions of insulin, promotes lipolysis, and increases circulating FFA levels, all of which can lead to insulin resistance." (PMID 21933140, 2011). "Also, decreases in muscle mass, both during the acute and recovery phases following injury, may significantly contribute to this persistent insulin resistance, since skeletal muscle has been shown to be responsible for 70–80% of whole-body insulin-stimulated glucose uptake." (PMID 21789167, 2011). "The positive relationships seen between TBARS and insulin and TBARS and HOMA-IR in the present study are in agreement with other study findings that increased ROS triggers insulin resistance." (PMID 21554710, 2011). "On the contrary, the combination of HFD and low doses of STZ resulted in characteristic of T2DM; HFD induces insulin resistance and low doses of intraperitoneal STZ induce moderate impairment of insulin secretion." (PMID 21439094, 2011). "VHF/S-fed mice also exhibited a reduced response to glucose clearance following insulin load relative to VHF- and C-fed mice; all features demonstrating a state of insulin resistance." (PMID 21966444, 2011). "Current research seeks to ameliorate insulin resistance by finding ways to increase PI3K/Akt activity and restore insulin sensitivity." (PMID 21935427, 2011). "A recent study showed that EA offers a beneficial effect on insulin resistance in obese and diabetic db/db mice, at least partly, via stimulation of SIRT1/PGC-1α, thus resulting in improved insulin signaling." (PMID 21754922, 2011). "Muscle gene expression was assessed in twenty-two seronegative HIV subjects (control), 21 HIV-infected individuals with normal insulin sensitivity (HIV-IS) and 19 HIV-infected individuals with insulin resistance (HIV-IR)." (PMID 21559208, 2011). "Eight-week glucose-fed rats exhibited insulin resistance (HOMA index), hypertension, tactile and cold allodynia and significant increases of plasma levels of glucose and insulin." (PMID 20830306, 2010). "Onset of intestinal inflammation precedes diet-induced increases in body weight, fat mass and insulin resistance and degree of TNF-α induction strongly correlates with diet-induced increases in weight, adiposity, plasma glucose, and insulin." (PMID 20808947, 2010). "11β-HSD1 knockout mice have improved insulin sensitivity, on the contrary transgenic overexpression of 11β-HSD1 in adipose tissue of mice results in insulin resistance." (PMID 21083914, 2010). "We conclude that in addition to insulin, at least one other biological proteinaceous factor exists that contributes to GLUT4 regulation and still functions in insulin resistance." (PMID 21187969, 2010). "Levels of HbA1c, fasting insulin, HOMA insulin resistance, triglyceride, and C-reactive protein were higher (though less so than among South Asians) and HDL-cholesterol non-significantly lower." (PMID 20421924, 2010). "To conclude, a 2-h post glucose insulin level is useful to detect and monitor all PCOS patients with insulin resistance." (PMID 21234175, 2010).
Insulin resistance (continued). "Insulin resistance, a central characteristic of the MS defined by WHO, is a state in which some organs become resistant to the effect of insulin that is needed to shuttle glucose into cells." (PMID 24281091, 2010). "Insulin sensitivity derived from the OGTT was significantly increased (pdom = 0.0010, adjusted effect size 15%) and insulin resistance derived from fasting state (HOMAIR) was accordingly nominally decreased in carriers of the minor allele (pdom = 0.0232)." (PMID 20534142, 2010). "In gastrocnemius muscle, insulin increased Akt phosphorylation in the F0-C group, whereas this response was completely blunted in the F0-BPA10 group, consistent with severe insulin resistance." (PMID 20488778, 2010). "In conclusion, apocynin has the potential to improve insulin sensitivity through ameliorating inflammatory status in the blood, liver, and adipose tissue of the C57BL/6 mice in which insulin resistance was induced by HFD." (PMID 21403905, 2010). "Our results regarding MetS prevalence, insulin levels, and HOMA-IR values suggest that women have a higher propensity to insulin resistance." (PMID 20374655, 2010). "This reduction in glucose levels was accompanied by a moderate decrease in serum insulin levels, suggesting that GHSR antagonists ameliorated insulin resistance in the long term." (PMID 20700401, 2010). "If there is any suspicion of metabolic syndrome insulin, C-peptide, glucose, Glycosylated Hemoglobin (HbA1c), triglycerides, cholesterol, Lipoproteins (HDL and LDL) estimations are necessary to detect insulin resistance or metabolic syndrome." (PMID 21188021, 2010). "Glitazones act on insulin resistance and the incretin mimetics target the other facets of metabolic defects of T2DM, namely the abnormalities of defective insulin secretion and inappropriate glucagon secretion." (PMID 27713366, 2010). "Finally, from a biomedical perspective, the findings of this study support the hypothesis that trauma and innate immunity are linked to insulin signaling and suggest that IMCL may be a biomarker of insulin resistance in injury, aging, obesity and immuno-deficiency." (PMID 20596596, 2010). "Inflammatory cytokines like TNFα, can act as mediators of insulin resistance by impairing the tyrosine kinase activity of both the insulin receptor (IR) and insulin receptor substrate (IRS-1), thus inhibiting insulin signaling." (PMID 20634940, 2010). "These metabolites were also related to insulin resistance (as determined by the HOMA index) and interpreted as marking the metabolic consequences of excessive fat and protein intake, with impairment of insulin signaling and mitochondrial overload." (PMID 20526369, 2010). "A possible pathway is reduced insulin degradation by the anti-PDI, that leads to higher insulin and eventually insulin resistance." (PMID 20886095, 2010). "The insensitivity of liver cells to insulin mediated suppression of VLDL assembly is observed in fructose-induced insulin resistant hamster model, where insulin resistance is accompanied with hepatic inflammation." (PMID 20423497, 2010). "Correspondingly, hemin improved intraperitoneal glucose-tolerance (IPGTT), reduced insulin-tolerance (IPITT), and lowered insulin resistance (HOMA index), and the inability of insulin to enhance GLUT4 was overturned." (PMID 20508722, 2010). "Raised hepatic glucose output and a defect in early insulin secretion are characteristics of IFG, while peripheral insulin resistance is often characteristic of IGT." (PMID 20712905, 2010). "Elevated fasting glucose, insulin and FFA concentrations are all part of the phenotype seen in insulin resistance." (PMID 20576156, 2010). "In this paper we give an overview of what is known about the role of ghrelin in obesity, insulin resistance, T2DM, and cardiovascular disease, and how ghrelin is involved in the regulation of glucose, insulin, adipose tissue, and cardiovascular metabolism." (PMID 20700400, 2010).
Insulin resistance (continued). "A better understanding of the molecular mechanisms utilized by saturated NEFA and insulin to regulate IL-6 production in proinflammatory monocytes could identify targets for novel anti-inflammatory molecules that could reduce the incidence of complications from insulin resistance." (PMID 21054880, 2010). "It was recently reported that besides the impairment in insulin secretion, HD patients also possess a decrease in insulin sensitivity and an increase in insulin resistance suggesting that the progression of the insulin secretion defect may be a way to compensate for insulin resistance." (PMID 27713238, 2009). "Investigated quantitative phenotypes included fasting plasma glucose, serum insulin, and HOMAIR as measure of overall insulin resistance." (PMID 19292929, 2009). "Concomitant insulin resistance and insulin hypersensitivity in peripheral tissues may paradoxically coexist as observed in livers of lipodystrophic and ob/ob mice, as well as in Cdk4 knockout mice with defective pancreatic beta cell development and blunted insulin secretion." (PMID 19460132, 2009). "Future studies may employ other methods to more directly assess insulin resistance in patients, such as hyperinsulinaemic euglycaemic clamping techniques, homeostasis model assessment-estimated insulin resistance or the more recently developed quantitative insulin sensitivity check index." (PMID 19245691, 2009). "Insulin levels and glucose intolerance were higher in C57 HF mice than in FVB HF mice, suggesting more severe insulin resistance." (PMID 19325873, 2009). "There were significant associations between levels of sleep quality and concentrations of plasma insulin, total and LDL cholesterol, and index of insulin resistance." (PMID 19426521, 2009). "Our results demonstrate that increased plasma FFA levels during the insulin clamp correlated inversely with peripheral (muscle) insulin sensitivity (TGD/SSPI) and positively with hepatic insulin resistance (Clamp EGP × SSPI)." (PMID 19656356, 2009). "Areas under the curve (AUC) for glucose, insulin and C-peptide from pre-meal to 120 min after consumption of a liquid meal were calculated, as were homeostasis model assessments of insulin resistance (HOMA2-IR) and the Matsuda index of insulin sensitivity." (PMID 19476649, 2009). "The importance of IRS1 in insulin signalling is supported by the fact that decreased levels of IRS proteins, coupled with decreased levels of the IR itself, contribute to the insulin resistance in diabetic states in both rodents and humans." (PMID 19308256, 2009). "Median levels of fasting serum insulin and HOMA-IR (which reflects insulin resistance) markedly increased over time both in men and women." (PMID 19558646, 2009). "Given the cross-talk between adipose tissue, liver, and skeletal muscle that affects insulin sensitivity, protection from adipose tissue inflammation in the 12/15LO KO mice may be the primary site of action leading to protection from whole body insulin resistance." (PMID 19787041, 2009). "Since insulin resistance is nearly universal in the patients with NASH, and it plays a pivotal role in the pathogenesis of NASH, many studies attempted to employ insulin sensitizer as a therapeutic modality against NASH." (PMID 19416517, 2009). "The continued use of the TZDs is a strong testament to the utilityof insulin sensitization as a mode of action for treatment of T2DM, but alsounderscores the need for a safer treatment for insulin resistance." (PMID 18769500, 2008). "In conclusion, reduction of insulin resistance was provedto ameliorate ovulation rate in PCOS patients, but strong evidences to sustain the utility of insulin–sensitizing drugs as a therapeutic optionfor infertility are lacking." (PMID 20108521, 2008).
Insulin resistance (continued). "Metformin was the first insulin sensitizing drug to be given to the PCOS patients, initially with the purpose ofobtaining additional arguments regarding the involvement of insulin resistance in the PCOS pathogenesis." (PMID 20108521, 2008). "Fasting serum IGF-I concentrations were negatively correlated with fasting serum glucose, insulin, C-peptide, triglycerides, total LDL and VLDL cholesterol, homeostatic model assessment of insulin resistance (HOMA-IR), and age." (PMID 19902049, 2008). "Whilst a correlation between hypovitaminosis D and insulin resistance has been identified in pregnant women and obese adolescents randomised, controlled trials with vitamin D supplementation are sparse, especially in non-diabetic, insulin resistant, vitamin D deficient subjects." (PMID 18667086, 2008). "Insulin resistance is a strong contributor to polycystic ovarian syndrome (PCOS) and insulin-sensitizing drugs are the most effective agents to reverse anovulation due to PCOS." (PMID 17437648, 2007). "Aglucose/insulin tolerance test showed significant reductions ofboth the area under the glucose curve and the area under theinsulin curve with LG268, and insulin resistance was reducedapproximately 75%." (PMID 17497022, 2007). "Thus, the association of type 2 diabetes with cardiovascular disease may reflect determinants and consequences (including hyperinsulinaemia) of insulin resistance, or determinants and consequences (including hyperglycaemia) of reduced insulin secretion, or a combination of these processes." (PMID 17760500, 2007). "Fructose-fed animals (60 g/100 g diet) displayed decreased glucose/insulin (G/I) ratio and insulin sensitivity index (ISI0,120) indicating the development of insulin resistance." (PMID 17641743, 2007). "Given the early insulin resistance and hyperinsulinaemia in the young POKO mice, we expected to see increased insulin levels in mature POKO mice." (PMID 17465682, 2007). "Tyrosine phosphorylation of IRS-1 enhances insulin sensitivity, whereas serine phosphorylation of IRS-1 by S6 kinase induces insulin resistance." (PMID 19412415, 2007). "Those patients with either insulin resistance or AGT comprised the majority of PCOS affected patients (AGT + fasting insulin ≥17: 83%, AGT + glucose/insulin ratio ≥6.5: 85.1%, AGT + HOMAIR ≥ 2: 87.2%, and AGT + HOMAIR ≥ 3.8: 72.3%)." (PMID 16603055, 2006). "The more favorable effects of VLCARB on fasting and post prandial plasma insulin concentrations is a significant observation which indicates that this dietary pattern may be a useful strategy for the short-term management of subjects with insulin resistance and hypertriacylglycerolemia." (PMID 16403234, 2006). "Notably, Group A and B genes are either completely (Group A) or partially (Group B) normalized following 48 hours of fasting/ weight reduction, when insulin sensitivity has increased, suggesting they may be important to the development of hepatic insulin resistance during DIO." (PMID 15985155, 2005). "While VAT is a major predictor of insulin sensitivity in overweight and lean individuals, others have found abdominal SCAT to contribute to insulin resistance independently of VAT." (PMID 15530168, 2004). "Consequently, the elevated glucose levels observed in the drinking diabetics likely were not caused by alcohol’s effects on insulin levels, but may have resulted from an alcohol-induced increase in insulin resistance in those diabetics." (PMID 15706798, 1998). "Furthermore, Aβ promotes the degradation of INSR in brain capillaries and competes with insulin for binding to INSR to block INSR signalling, collectively contributing to insulin resistance in AD." (PMID 41566484, 2026). "Supraphysiological insulin exposure, as used in our in vitro model, can induce receptor and post-receptor desensitization, trigger insulin resistance and non-specific pathway activation (e.g., proliferation, anti-apoptosis, and Akt recruitment)." (PMID 41509918, 2026).
Insulin resistance (continued). "Together, they ultimately lower insulin levels and insulin resistance, although this effect is not yet well-documented." (PMID 41575482, 2026). "This second phase was diagnosed as SIR based on severe SC insulin resistance, normal IV insulin sensitivity, and lack of measurable insulin in the bloodstream after SC injection." (PMID 41472947, 2026). "Evidence suggests that the impairment in GIP-induced insulin secretion occurs after, rather than before, the onset of insulin resistance, making it more likely a consequence of the metabolic disorder leading to T2DM." (PMID 41575482, 2026). "Background/Objectives: The Metabolic Score for Insulin Resistance (METS-IR), a non-insulin-based index of insulin resistance (IR), and subclinical myocardial injury (SCMI), identified by electrocardiogram (ECG), are each associated with cardiovascular disease (CVD)." (PMID 41682822, 2026). "Marked SC insulin resistance was demonstrated following 20 units of SC human neutral insulin (Actrapid) with no insulin detectable in blood after 5 hours." (PMID 41472947, 2026). "Additionally, elevated ghrelin (GHRL) levels post-acupuncture correlated with improved insulin sensitivity, consistent with studies linking GHRL to insulin resistance mitigation in PCOS." (PMID 41514462, 2026). "The model incorporating AIP, together with insulin, HbA1c, and insulin resistance indices, did not significantly predict circulating irisin levels (model p = 0.494, adj." (PMID 41596434, 2026). "In this cohort of young children, both insulin levels and HOMA‐IR, an index of insulin resistance that considers fasting glucose and insulin levels, were positively associated with PBMC basal and maximal respiration as well as the ratio of mitochondrial respiration and glycolysis (OCR/PER)." (PMID 40525760, 2025). "A paradox of hepatic insulin resistance is that, while the insulin-resistant liver fails to suppress gluconeogenesis—contributing to hyperglycemia—it often remains sensitive to insulin’s lipogenic effects, promoting de novo lipogenesis and hepatic steatosis." (PMID 41150735, 2025). "In contrast, type 2 diabetes arises from a non-autoimmune, progressive decline in β-cell insulin secretion, often occurring alongside insulin resistance and metabolic syndrome." (PMID 41155203, 2025). "Subsequent pathway analysis revealed impaired insulin signaling in the MFP of PyMT-RIDad mice marked by downregulation of the PI3K-Akt pathway, further linking RIDα/β overexpression to insulin resistance." (PMID 40526430, 2025). "It is important to note that the difference in metabolic response may be due to the severity of insulin resistance in GDM-I patients, which necessitates insulin therapy." (PMID 40136665, 2025). "In our study, insulin resistance is also correlated with an elevated frequency of insulin-specific CD8 T cells, independent of BMIp." (PMID 39656436, 2025). "Additionally, the JAK/STAT pathway, activated by IL-6, contributes to insulin resistance by inducing the expression of SOCS proteins, which inhibit insulin receptor signaling, impairing normal insulin function." (PMID 40004236, 2025). "While the 24‐week exposure to concentrated PM2.5 impairs insulin sensitivity, 30‐day exposure neither induced glucose intolerance nor insulin resistance in male or female mice." (PMID 40892707, 2025). "The precise effect of progesterone on β-cells remains elusive, but it has been suggested that insulin resistance results from reduced insulin binding, downregulation of the GLUT4 receptor (responsible for glucose uptake in muscle and adipose tissue) and insulin-induced hepatic gluconeogenesis." (PMID 40235646, 2025). "Among the most commonly prescribed are metformin and α-glucosidase inhibitors, which help to regulate key metabolic and inflammatory parameters such as fasting plasma glucose (FPG), fasting insulin (FINS), glycated hemoglobin (HbA1c), and homeostasis model assessment of insulin resistance (HOMA-IR)." (PMID 40771277, 2025).